LINC00865 (long independently transcribed non-coding RNA 865)
Synonyms: TCONS_00018278; LINC01374
Gene: Long non-coding RNA gene on chromosome 10 (89,829,483 to 90,225,443, forward strand). Ensembl gene ENSG00000232229.
Diseases named in the same sentence as LINC00865 in open-access papers:
LINC00865 is named in the same sentence as 1 disease in open-access papers, as found by Europe PMC text mining. Sharing a sentence is not in itself a finding about the gene and the disease. The quoted sentences say what the papers report.
tumour (1 paper, 2023). "RT–qPCR results showed that LINC00924, LINC00944, and LINC00865 were highly expressed in tumour tissues, while LINC00702 and ZFAS1 were expressed at low levels in tumour tissues." (PMID 36936957, 2023).